H19 (H19 imprinted maternally expressed transcript)
Diseases named in the same sentence as H19 in open-access papers (continued):
Sharing a sentence is not in itself a finding about the gene and the disease.
colorectal cancer (142 papers, 2011 to 2025). A primary or metastatic malignant neoplasm that affects the colon or rectum. "Several lncRNAs originating from cancer-associated fibroblasts (CAFs), such as CCAL and H19, have also been found to play key roles in the development of oxaliplatin resistance in colorectal cancer." (PMID 40781643, 2025). "For instance, exosomal lncRNA H19 is associated with drug resistance in colorectal cancer, while exosomal lncRNA PVT1 is implicated in gastric cancer." (PMID 40781643, 2025). "For example, lncRNA H19 derived from carcinoma-associated fibroblasts (CAFs) contributes to the stemness and chemoresistance of colorectal cancer by targeting miR-141." (PMID 33665192, 2021). "Related research reports indicate that H19 gene mutations are linked to the risk of colorectal cancer." (PMID 34922547, 2021). "For example, LncRNA H19 expression is significantly upregulated in primary and metastatic foci of colorectal cancer and is associated with poor prognosis in colorectal cancer." (PMID 34081618, 2021). "To further confirmed the association between H19, hnrnpA2B1 and Raf-1, we analyzed the expression of H19, hnrnpA2B1 and Raf-1 in the primary colorectal cancer tissues and demonstrated the expression of H19 is positive correlated with Raf-1." (PMID 32698890, 2020). "Consistent with our results, several other studies have also demonstrated H19 rs2839698 variant to be a risk factor for gastrointestinal cancer, colorectal cancer, and hepatocellular cancer." (PMID 32509581, 2020). "To validated the association between H19 and EMT in colorectal cancer, we first confirmed the influence of H19 on the expression of EMT transcript factors in CRC cells because of their direct functions to induce EMT." (PMID 32698890, 2020). "It was reported that rs3024270 C>G, rs2839698 G>A, and rs217727 G>A dramatically altered the secondary structure of H19, and the rs3024270 GG genotype was associated with an increased risk of colorectal cancer in a Chinese population." (PMID 30890582, 2019). "The present study is for the first time to evaluate the association of genetic variations in the H19 promoter region with advanced colorectal cancer (CRC) susceptibility, environmental factors, and clinical outcomes." (PMID 31452627, 2019). "We found that H19, a cancer lncRNA that is associated with many cancer types, including colorectal cancer, was functionally associated with the purine metabolism subpathway." (PMID 28152521, 2017). "To further understand the significance of H19 overexpression in colorectal cancer, we set out to identify the potential associations between H19 expression and patients' clinicopathological features." (PMID 26989025, 2016). "In this study, we conducted a case-control study to genotype the candidate SNPs in H19 (rs2839698, rs3024270, rs217727, and rs2735971) and investigate the association with the risk of colorectal cancer." (PMID 27027436, 2016). "In summary, we have provided the evidence that H19 rs2839689 contributes to the susceptible to colorectal cancer in the Chinese population." (PMID 27027436, 2016). "We conducted a case-control study to evaluate the association between four selected single nucleotide polymorphisms (SNPs) (rs2839698, rs3024270, rs217727, and rs2735971) in H19 and the risk of colorectal cancer in a Chinese population." (PMID 27027436, 2016). "However, the specific functions of H19 in colorectal cancer (CRC) metastasis and the underlying mechanism are still largely unclear." (PMID 32698890, 2020). "In addition, some researchers pointed out that H19 was associated with a poor prognosis in colorectal cancer, which promoted tumor growth by recruiting and binding to eIF4A3." (PMID 28658310, 2017). "Our results provided the evidence that rs2839698 in H19 was associated with elevated risk of colorectal cancer, which may be a potential biomarker for predicting colorectal cancer susceptibility." (PMID 27027436, 2016).
colorectal cancer (continued). "Besides, we calculated genotype frequencies of H19 tagSNPs among cases and controls and their associations with colorectal cancer risk according to variant genetic effect models (additive, dominant, recessive and co-dominant models)." (PMID 27027436, 2016). "In this study, we aim to explore whether H19 polymorphisms are related to the susceptibility of colorectal cancer." (PMID 27027436, 2016). "Studies have shown that H19 can encode miR-675 and encoding miR-675 might be one of the important roles of H19 in human placental trophoblast cells and colorectal cancer cells." (PMID 24810858, 2014). "However, depletion of H19 caused increased polyp count in a mouse model for colorectal cancer, larger tumor growth in a mouse teratocarcinoma model and an earlier development of tumours in a mouse hepatocarcinoma model." (PMID 23887658, 2013). "Moreover, H19 is also associated with the stemness of colorectal cancer cells." (PMID 33291403, 2020). "In colorectal cancer, H19 promotes cancer cell stemness and resistance to oxaliplatin by acting as a ceRNA that mute miR-141, a microRNA known to suppress cancer stemness by targeting the β-catenin to block the WNT/β-catenin pathway." (PMID 40781643, 2025). "For example, lncRNA H19 promotes colorectal cancer resistance to oxaliplatin by sequestering miR-141." (PMID 40781643, 2025). "H19 inhibits colorectal cancer by upregulating miR-29b-3p expression, thus suppressing tumor growth." (PMID 40191723, 2025). "The long noncoding RNA H19 plays a significant role in chemoresistance across various cancers, including glioma, breast cancer and colorectal cancer." (PMID 39940704, 2025). "In another study, increased expression of H19 was reported in colorectal cancer (CRC) under hypoxic conditions or in oxiplatin-treated CRC cells." (PMID 39940704, 2025). "Conversely, in colorectal cancer cells, the loss or knockdown of HDAC2 induces EMT and lung metastasis by upregulating the long non-coding RNA H19 (lncRNA H19)." (PMID 39620228, 2024). "Meanwhile, CAFs can increase colorectal cancer stem cell properties and chemoresistance by conveying exosomal lncRNA H19 into colorectal cancer cells." (PMID 38521881, 2024). "In this paper, we found, that in colorectal cancer cells, the long non-coding RNA H19 can bind immature RNAs and splicing factors as hnRNPM and RBFOX2." (PMID 39098911, 2024). "The lncRNA H19, which has oncogenic properties in colorectal cancer, mediates 5-fluorouracil resistance by sponging miR-194–5p to elevate SIRT1 expression, thus promoting autophagy-induced resistance to 5-fluorouracil in colorectal tumors." (PMID 39403142, 2024). "H19 has also been found in EVs released from tumor stromal cells (CAF) during colorectal cancer, enhancing oxaliplatin resistance both in vivo and in vitro." (PMID 36831417, 2023). "H19 has been reported to competitively bind to miR-200a and indirectly regulate β-catenin in colorectal cancer." (PMID 36873948, 2023). "LncRNA H19 was overexpressed in tumor tissues and facilitated the stemness and chemoresistance of colorectal cancer (CRC) through the regulation of CAFs." (PMID 37784036, 2023). "In another study, lncRNA H19 was expressed to a great extent in the CAFs of colorectal cancer patients, which also increased with cancer progression." (PMID 36901813, 2023). "Similar to observed in resistance against MTX, H19 also modulates resistance against oxaliplatin in colorectal cancer cells by activation of the β-catenin signaling pathway." (PMID 35955440, 2022). "Through integrative bioinformatics analysis, H19 is observed to play key roles in the process of oxaliplatin or irinotecan resistance in colorectal cancer." (PMID 36246634, 2022). "Ectopic H19 expression increases ex vivo metastasis of colorectal cancer cells and induces epithelial to mesenchymal transition (EMT)." (PMID 34081618, 2021).
colorectal cancer (continued). "A previous study also reported that lncRNA H19 activates Wnt signaling and promotes epithelial-mesenchymal transition in colorectal cancer cells." (PMID 34922547, 2021). "In colorectal cancer cells, H19 mediates miR-138 by sponging it and subsequently enhances the expression of HMGA1, thereby enhancing the invasion ability of cancer cells." (PMID 34583640, 2021). "In colorectal cancer, H19 acts as a competing endogenous RNA, leading to the up‐regulation of ZEB1/2 protein expression." (PMID 34977870, 2021). "H19 acts in colorectal cancer as a microRNA sponge for MiR-138 and MiR-200, which then target zinc finger e-box binding homeobox 1 (ZEB1) and ZEB2 that are important mesenchymal cell markers in EMT." (PMID 33193379, 2020). "Functional analyses demonstrated that H19 promotes the metastases of colorectal cancer cells both in vitro and in vivo." (PMID 32698890, 2020). "Ectopic H19 expression promoted the metastasis of colorectal cancer cells in vitro and in vivo, and induced epithelial-to-mesenchymal transition (EMT)." (PMID 32698890, 2020). "Through the exosomal transport of H19, CAFs activate the Wnt/β-catenin signaling in colorectal cancer cells, facilitating cancer stemness and drug resistance." (PMID 33050576, 2020). "Long non‐coding RNA (lncRNA) H19 is involved in the carcinogenesis, progression, and metastasis of colorectal cancer (CRC)." (PMID 32207861, 2020). "In the present study, we demonstrate H19 promotes the migration, invasion and metastasis of colorectal cancer cells in vitro and in vivo." (PMID 32698890, 2020). "For instance, lncRNA H19 demonstrates a poor prognosis of colorectal cancer and enhances tumor growth via recruiting eIF4A3." (PMID 32549791, 2020). "For example, lncRNA H19 is overexpressed in colorectal cancer and increases the intracellular aldehyde dehydrogenase (ALDH) activity in colorectal tumors." (PMID 32164712, 2020). "In conclusion, our finding reveals that lncRNA H19 is upregulated in colorectal cancer, and correlated with poor outcomes in CRC patients." (PMID 32698890, 2020). "For instance, it has been demonstrated that lncRNA H19 overexpression induces the EMT of colorectal cancer (CRC) cells by sponging miR-29b-3p to directly upregulate PGRN and activate Wnt axis." (PMID 32727450, 2020). "Our data suggest that reduced H19 expression induced cell apoptosis through miR675, which was confirmed in human colorectal cancer cells." (PMID 32323721, 2020). "It has been also demonstrated that lncRNA H19 sponges miR‐141 and contributes to tumour development and chemoresistance in human colorectal cancer." (PMID 32885590, 2020). "LncRNA H19 activates the β-catenin pathway by sequestering miR-141, which contributes to tumor development and chemoresistance in colorectal cancer tumors." (PMID 32164712, 2020). "Recent studies have confirmed that H19 lncRNA has an oncogenic function in a variety of adult cancers, such as hepatocellular carcinoma, colorectal cancer, pancreatic cancer, and glioma cell." (PMID 32978516, 2020). "Considering the increased expression and a potential pro-metastasis role of H19 in colorectal cancer, the effect of H19 on the invasiveness of CRC cells were evaluated in vitro." (PMID 32698890, 2020). "H19 overexpression in colorectal cancer cells promotes cancer stem cell-like phenotypes and oxaliplatin resistance." (PMID 33050576, 2020). "LncRNA H19 boosts tumor growth and predicts a poor prognosis in colorectal cancer through recruiting eIF4A3." (PMID 32549791, 2020). "In the current study, we identified lncRNA H19 as one of the lncRNAs increased most substantially in primary colorectal cancer tissues, which was further upregulated in metastatic tissues by analyzing public dataset and confirmed with clinical specimens." (PMID 32698890, 2020). "LncRNA known to be up-regulated in colorectal cancer, such as H19 and CCAT1, were confirmed in our RNA-seq analysis." (PMID 32082365, 2019).
colorectal cancer (continued). "Overall, H19 promoted EMT in colorectal cancer via a novel ceRNA network of H19/miR-29-3b/PGRN/Wnt signaling axis." (PMID 31744051, 2019). "A recent study reported that lncRNA H19 is a miRNA 200a sponge that inhibits miRNA 200a functions, thereby promoting cell proliferation in colorectal cancer." (PMID 30984308, 2019). "This study aimed to develop a competing endogenous RNA (ceRNA) network to elucidate the role of long non-coding RNA H19 in colorectal cancer." (PMID 31164794, 2019). "In colorectal cancer, the lncRNA H19 was reported to derepress the endogenous genes, Vimentin, ZEB1, and ZEB2, by targeting miR138 and miR200a." (PMID 31752684, 2019). "To verify the conclusions derived from bioinformatics analysis, we investigated the effect of lncRNA H19 knockdown in human colorectal cancer cell lines HT-29 and HCT116." (PMID 31164794, 2019). "Our previous work revealed that H19 promotes tumor growth by recruiting and binding to eIF4A322, indicating poor prognosis of colorectal cancer." (PMID 30451820, 2018). "In the further functional studies, we confirmed that H19 down or up-regulation altered IC50 value for 5-Fu in colorectal cancer cells." (PMID 30451820, 2018). "In colorectal cancer, it has been shown that H19 becomes significantly upregulated in methotrexate-resistant cells, with H19 knockdown sensitizing methotrexate resistance in this cell line." (PMID 30619763, 2018). "Previously, we found H19 indicated a poor prognosis of colorectal cancer and promoted tumor growth by recruiting and binding to eIF4A322." (PMID 30451820, 2018). "Some studies have reported various lncRNAs acting as ceRNAs to regulate the EMT process, such as lncRNA HULC in hepatocellular carcinoma and lncRNA H19 in colorectal cancer." (PMID 28697764, 2017). "For example, the lncRNA H19, serving as a miRNA sponge, accelerates the development process of colorectal cancer." (PMID 28544557, 2017). "H19 promotes epithelial to mesenchymal transition by functioning as miRNA sponges in colorectal cancer." (PMID 27716361, 2016). "For example,the LncRNA H19 as a ceRNA for miR-138 and miR-200a promotes epithelial to mesenchymal transition by functioning as miRNA sponges in colorectal cancer." (PMID 27276011, 2016). "In colorectal cancer, H19 acted as miRNA sponges to restore activation of multiple oncogenes, which promoted epithelial-to-mesenchymal transition (EMT) and were inherently suppressed by miR-138 and miR-200a." (PMID 27738631, 2016). "Moreover, we found that increased colorectal cancer risk correlated with rs2839698 was more remarkable in subgroups of younger individuals and male, suggested that promoting effects of H19 variants on colorectal cancer may be modulated by specific epidemiological features." (PMID 27027436, 2016). "The long non-coding RNA (lncRNA) gene, H19, has been involving in multiple biological functions, which also plays a vital role in colorectal cancer carcinogenesis." (PMID 27027436, 2016). "In this study, we selected four tagSNPs (rs2839698, rs3024270, rs217727, and rs2735971) in H19 gene and DMR to estimate the association between these variants and colorectal cancer susceptibility." (PMID 27027436, 2016). "This TGF-β dependent induction of H19 has been recently corroborated in an experimental model of colorectal cancer." (PMID 26536864, 2015). "mir675 is shown to up-regulate the essential cartilage matrix component COL2A1 essential in cartilage regeneration, while both H19 and mir675 are found to be upregulated in human colon cancer and primary human colorectal cancers." (PMID 24587348, 2014). "In human colorectal cancer, lncRNA H19 and H19-derived miR-675 are overexpressed in cell lines and primary tissues but not in adjacent noncancerous tissues." (PMID 23843741, 2013). "Recently, this H19-derived miR-675 was shown to regulate tumor suppressor RB in human colorectal cancer favoring its progression." (PMID 22662250, 2012).
colorectal cancer (continued). "Notably, H19, previously discussed in the context of cancer development, has been shown to contribute to colorectal cancer chemoresistance through distinct mechanisms." (PMID 40781643, 2025). "Accordingly, givinostat, a pan-HDAC inhibitor, favored H19 expression in colorectal cancer cells." (PMID 40885718, 2025). "In addition, in colorectal cancer, they have been reported to activate the Wnt/β-catenin pathway via the exosomal lncRNA H19, thereby maintaining colorectal cancer cells’ stemness." (PMID 40296919, 2025). "Overexpression of H19 in colorectal cancer has also been reported." (PMID 37189829, 2023). "HOTTIP could maintain the stemness of cancer stem cells (PCSCs) through the HOTTIP/WDR5/HOXA9/Wnt axis in pancreatic cancer; lncRNA H19 mediated the methotrexate resistance in colorectal cancer through activating Wnt/β-catenin signaling." (PMID 34690755, 2021). "After induction of colorectal cancer, the H19 knockout model presented twice more polyps, suggesting that the H19 may play a role in the initiation and progression of tumorigenesis acting as a tumor suppressor gene." (PMID 34526543, 2021). "Furthermore, knockdown of hnRNPA2B1 reversed the phosphorylation of ERK and upregulation of Snail in colorectal cancer cells with stable H19 overexpression." (PMID 32698890, 2020). "Thus, the distribution of hnRNPA2B1 in H19 overexpression and control colorectal cancer cells were compared." (PMID 32698890, 2020). "Collectively, we suggested that H19 could be a potential prognosis biomarker and therapeutic target for colorectal cancer." (PMID 32698890, 2020). "Moreover, the expression of H19 in colorectal cancer cells with low HDAC2 expression is higher than that in cells with high HDAC2 expression." (PMID 33267897, 2020). "LncRNA H19 is highly expressed in colorectal cancer cells, and can be utilized as miRNA sponges to promote the transformation of epithelial cells into stromal cells, as well as promote the proliferation and carcinogenic activities of colorectal cancer cells." (PMID 31123170, 2019). "These include but are not restricted to lncRNAs like HOTAIR, Pvt1, RoR, prostate cancer–associated transcript 1 (PCAT1), ANRIL, H19, nuclear enriched abundant transcript 1 (NEAT1), UCA1, lung adenocarcinoma transcript 1 (LUADT1), colorectal cancer–associated lncRNA (CCAL), and many more." (PMID 30296263, 2018). "In the current study, however, we didn’t get similar results of H19 in the chemoresistance of CRC against oxaliplatin, which is also platinum-based drug used extensively for treating colorectal cancer, suggesting that versatile function of H19 in different type of cancer should be considered." (PMID 30451820, 2018). "Biological and clinical relevance of H19 in colorectal cancer patients has been reported recently." (PMID 30517191, 2018). "In colorectal cancer H19 interacts with miR-200a and miR138 to boost Vimentin and ZEB1 expression." (PMID 28327666, 2017). "H19, a paternally imprinted noncoding RNA, has been found to be overexpressed in various cancers, including colorectal cancer (CRC), and may function as an oncogene." (PMID 28164117, 2017). "The well-known lncRNA H19, which play important roles in multiple cancers such as liver, breast and colorectal cancers, has recently been proved to act as miRNA sponge for miR-138 and miR-200a to promote the transition from epithelial to mesenchymal in colorectal cancer." (PMID 27580177, 2016). "LncRNA H19 has been found to be aberrantly expressed in many cancers including breast, esophageal, bladder, and colorectal cancers and may be involved in the carcinogenesis of these cancers by targeting the downstream microRNAs." (PMID 27486980, 2016). "The fact that H19 is also the precursor of miR-675, known to downregulate the retinoblastoma (RB) gene in human colorectal cancer, adds a further level of complexity to the functional roles that H19 may have in different signaling pathways and cell contexts." (PMID 27177333, 2016).